CD44 (CD44 molecule (IN blood group))
Diseases named in the same sentence as CD44 in open-access papers (continued):
Sharing a sentence is not in itself a finding about the gene and the disease.
ovarian carcinoma (continued). "Based on our preliminary studies, we initiated the present study to investigate the correlation between expression of CD44 and its associated structural oligosaccharide Lewis y antigen and resistance to therapy and prognosis for ovarian cancer." (PMID 23468946, 2013). "A majority (71%) of 31 ovarian cancer samples analyzed expressed a complex pattern of CD44 splice variants." (PMID 23782518, 2013). "Over-expression of Lewis y and CD44 antigen are strong risk factors for chemotherapeutic drug resistance in ovarian carcinoma patients." (PMID 23468946, 2013). "Results from binary logistic regression analysis surgical stage, residual tumor size and expression of CD44 and Lewis y antigen in ovarian carcinoma tissues were independent risk factors for chemotherapeutic drug resistance." (PMID 23468946, 2013). "Surgical stage, residual tumor size and expression of CD44 and Lewis y antigen in ovarian carcinoma tissues were independent risk factors for chemotherapeutic drug resistance." (PMID 23468946, 2013). "In the ovarian cancer, the early progenitor cells are associated with some specific surface markers like CD44, CD133 and CD117." (PMID 22642602, 2012). "Multivariate analysis of overall survival demonstrated that a high pretreatment serum level of soluble CD44 isoform v5 is independently associated with favourable clinical outcome in ovarian cancer." (PMID 9413956, 1997). "Evaluation of the expression of solCD44std, solCD44v5, and solCD44v6 in ovarian cancer through both IHC and serological analyses suggested that CD44 splice variants are expressed at low levels in malignant ovarian tumors and that their serum levels do not reliably reflect the tumor burden." (PMID 41440277, 2025). "Regardless of the potential mechanisms, which extend beyond the scope of this study, our results suggest that VDR (together with CD44) may serve as a valuable diagnostic marker for the HGSC type of ovarian cancer." (PMID 40332380, 2025). "Interestingly, we have found that ovarian cancer tissues with high expressions of PD-L1 were associated with high expressions of stem cells expressing CD44 and LGR5." (PMID 36604635, 2023). "Furthermore, CD44 was associated with benefits of targeted therapeutic relapse-free survival (RFS) at 12 months in ovarian cancer, with an AUC of 0.733." (PMID 37117249, 2023). "Expression of both ALDH1 and CD44 is associated with CSC populations in ovarian cancer." (PMID 35820889, 2022). "Interestingly, several studies found CD44 expression to be associated with CSC-like properties of ovarian cancer cells." (PMID 34680456, 2021). "The expression of CD117 and CD44, which has been associated with a cancer stem cell phenotype in ovarian cancer, was found in up to 90% of EpCAM+/CD45+ ovarian cancer hybrid cells indicating an association of cell fusion with the origin of cancer stem/initiating cells." (PMID 34503305, 2021). "CD44 and its variants represent promising targets for ovarian cancer immunotherapy." (PMID 34680456, 2021). "Importantly, upregulation of CD44 in ovarian cancer has been shown to be strongly associated with the occurrence of metastasis and disease relapse." (PMID 33335857, 2020). "Hence, expressions of key regulators AKT1, KRAS, EPCAM and CD44 can be correlated to increasing or decreasing the risk of disease progression, so, they can be potential prognostics markers or drug targets in ovarian cancer." (PMID 31752757, 2019). "Among the included studies, 17 articles assessed the correlation between the expression of CD44 or its isoforms and the clinicopathological features of ovarian cancer, whereas the association of CD44 expression with OS or DFS was examined using the Kaplan–Meier method in 12 of these studies." (PMID 28070170, 2017). "However, studies on isoforms containing different individual variant exons in ovarian cancer have generally suggested improved overall survival associated with splice isoforms of CD44." (PMID 27253518, 2016).
ovarian carcinoma (continued). "This group then followed up reporting significant correlations between expression of Lewis y antigen and CD44 in tissues from ovarian cancer patients, where overexpression of Lewis y and CD44 antigen were strong predictive risk factors for chemotherapeutic drug resistance." (PMID 26569327, 2015). "Also in ovarian cancer, increased density of CD44 positive cells was associated with chemotherapy resistance." (PMID 25230021, 2014). "In addition, the number of CD44+ EOC stem cells was significantly higher in patients with early-stage ovarian cancer (FIGO I/II), and it was associated with shorter progression-free survival (P = 0.026)." (PMID 21904548, 2011). "Ovarian cancers express standard and variant isoforms of CD44." (PMID 21541039, 2011). "Moreover, ovarian cancer may be caused by ovarian cancer-initiating cells characterized by surface antigen CD44 and the ovarian CSC maker c-KIT (CD117)." (PMID 33014829, 2020). "We observed positive correlations between SPHK1 expression and CD44 in ovarian cancer patient tissues." (PMID 40356021, 2025). "A route to inhibit angiogenesis is provided by HA-coated siRNA nanocarriers targeting CD44 on tumour endothelium; this integrates vascular, stromal and immune targeting into multifunctional ovarian cancer nanomedicines." (PMID 41514600, 2025). "Given the critical role of CD44 in cancer metastasis and therapeutic resistance, several strategies targeting CD44 have been developed for the treatment of diverse malignancies, including head and neck, breast, gynecological, and ovarian cancers." (PMID 41009730, 2025). "In a recent study, treatment of primary ovarian cancer cells, harvested from ascites of an ovarian cancer patient, simultaneously using CD44-CAR-NK cells and cisplatin led to increased anti-tumor cytotoxicity, compared with monotherapies alone." (PMID 40519903, 2025). "SHMT2 decreased, while SHMT2α increased stem cell like features of ovarian cancer cells, as identified by spheroid formation ability, expression of stemness markers CD44 and CD133." (PMID 40097394, 2025). "The combination of CD44, CD133, and VDR as potential diagnostic markers in ovarian cancer is supported by their roles in cancer stem cell biology, their association with aggressive tumor characteristics, and their influence on clinical outcomes." (PMID 40332380, 2025). "Some researchers have used gold NPs loaded with cisplatin in ovarian cancer against the CD44 marker." (PMID 40142941, 2025). "In MDA-MB-231 breast and SKOV-3 ovarian cancer cells, HA molecules of 500 kDa and 1000 kDa indirectly activate Rho pathways through CD44, promoting cell growth and migration." (PMID 40507943, 2025). "Hyaluronic acid-decorated carriers frequently exploit CD44 to deliver cytotoxins or to deliver MDR1 siRNA selectively to chemoresistant CD44-overexpressing ovarian cancer cells." (PMID 41514600, 2025). "Among our identified binding motifs, X-aptamer motif 3 and motif 5 showed enhanced binding affinity to CD44-overexpressing human ovarian cancer IGROV cells with ADDA form, compared to the binding affinities with amine form and scrambled sequence." (PMID 40001633, 2025). "MiR-199a overexpression in CD44+ cancer-initiating cells (CICs) in ovarian cancer xenografts significantly decreased tumor volume." (PMID 40114966, 2025). "In CD44+ ovarian cancer cells, MDR1 downregulation increased apoptosis and suppressed ovarian cancer growth." (PMID 38672650, 2024). "Several established ovarian cancer stem cell markers, including CD44, CD117, CD133, CD24, and ALDH have been used to identify ovarian cancer stem cell populations." (PMID 39224110, 2024). "Exosomal CD44 has been reported to enhance the capacity of ovarian cancer cells to invade via CD44 transfer to the peritoneal mesothelium." (PMID 38178187, 2024). "CD44 was also found on ovarian cancer-derived exosomes, which transfer this molecule to mesothelial cells, thereby promoting adhesion." (PMID 38783165, 2024).
ovarian carcinoma (continued). "DLX4 induces CD44 by stimulating IL-1β-mediated NF-κB activity, thereby promoting ovarian cancer metastasis." (PMID 38317839, 2024). "Blocking of the CD44 gene via RNA interference (RNAi) was reported to significantly inhibit ovarian cancer cell growth and tumour blood vessel formation and reduce disease recurrence and metastasis." (PMID 39125873, 2024). "The stem cell markers LGR5, Oct4, and CD44 were highly expressed in the ovarian cancer cell lines ES2, OVCAR8, and OVCAR3." (PMID 38275417, 2024). "The effects of the surface architecture of the modified NPs on their binding to ovarian cancer cells overexpressing CD44 were investigated in a separate study." (PMID 39125873, 2024). "Hyaluronic acid (HA) is frequently added to the surface of NPs to target CD44, particularly in ovarian cancer and stem cells, to prevent metastasis and overcome drug resistance." (PMID 39125873, 2024). "In ovarian cancer, an RNA‐based bispecific CD44–EpCAM aptamer was shown to inhibit cell growth and to induce apoptosis by blocking CD44 and EpCAM simultaneously." (PMID 38783892, 2024). "Stimulating the expression of CD44 in monocytes promotes apoptosis of ovarian cancer cells, favoring immune suppression." (PMID 38166541, 2024). "Ovarian cancer cells express the homing cell adhesion molecule CD44 on their surface, which interacts with hyaluronic acid and mediates intraperitoneal adhesion." (PMID 38783165, 2024). "As such, an anti-human CD44 mAb was employed to direct glycosylated PTX-loaded liposomes to CD44-positive ovarian cancer cells with great success." (PMID 36678845, 2023). "According to our previous research, both E-selectin and CD44 are highly expressed in ovarian cancer tissue." (PMID 37046797, 2023). "In line with our findings, GDF15 promotes the immune escape of ovarian cancer by targeting CD44 in dendritic cells." (PMID 36776876, 2023). "The clinical significance and prognostic value of CD44 as a CSC surface marker in patients with ovarian cancer remain controversial." (PMID 38201468, 2023). "Previous studies have reported the existence of a subpopulation of embryonic stem cell-like cells in ovarian cancer tissues, which highly express CD44, CD133, and c-Kit (CD117)." (PMID 38021163, 2023). "On the other hand, the microRNA-200c that deters EMT inhibits metastasis of CD117+CD44+ ovarian cancer stem cells." (PMID 36375842, 2023). "We found that CD44 protein expression levels were markedly higher in ovarian cancer tissues compared to healthy liver tissues." (PMID 37284314, 2023). "CD44 transfer from tumor cells to mesothelial cells via exosomes results in increased MMP-9 secretion by mesothelial cells that induces ovarian cancer invasion in vitro." (PMID 37545408, 2023). "We found that normal ovarian cancer cells (CD44-/CD133-) had high expression levels, while miR-134-3p expression was extremely low in HuOCSCs 18, suggesting that miR-134-3p is inversely correlated with the malignancy of ovarian cancer." (PMID 38021163, 2023). "The NK cell line NK-92 carrying a third-generation pan-CD44 CAR also showed cytotoxic activity against ovarian cancer in vitro." (PMID 37240385, 2023). "Literature data on the role of CD44 in the progression of ovarian cancer, and its relation to clinical data, are also mixed and often contradictory." (PMID 36768723, 2023). "The HA receptor CD44 has also been shown to be upregulated in both mesothelial cells and macrophages isolated from the ascites of patients with ovarian cancer compared with benign ascites." (PMID 37545408, 2023). "We found that the expression of the CD44 gene was associated with lower FIGO stage and, hence, better OS and DFS of ovarian cancer patients." (PMID 37628927, 2023). "For further demonstration of the ovarian cancer microenvironment, we have investigated cancer stem cells expressing CD44, LGR5 and ALDH2." (PMID 36604635, 2023).
ovarian carcinoma (continued). "Cells positive for CD44 and MyD88 in epithelial ovarian cancer demonstrated increased cytokine/chemokine production, an enhanced formation of spheroids, increased repair capacity, and chemoresistance." (PMID 38201468, 2023). "In this paper, we reported the higher uptake of ESBP-BSANPs-FITC in ovarian cancer cells with low CD44 expression (A2780/CP70 and ID8) than that of BSANPs-FITC, and the lower IC50 of ESBP-BSANPs-PTX in these cell lines than that of free PTX." (PMID 37046797, 2023). "The expression of CD44 was also found to be increased in patients with chemotherapy-resistant epithelial ovarian cancer." (PMID 38201468, 2023). "A histopathological study in patient samples with ovarian cancer revealed that high CD44 expression correlates with tumor stage, grade, histological subtype, and poorer survival outcomes." (PMID 37545408, 2023). "The restoration of miR-199a-5p expression in ovarian cancer cells has been shown to increase sensitivity to cisplatin through targeting both mTOR and CD44, thereby reducing ovarian cancer stem cell levels." (PMID 37835506, 2023). "A meta-analysis based on 18 studies involving more than 2000 patients with ovarian cancer demonstrated that the expression of CD44 correlated with a high TMN (Classification of Malignant Tumour) stage and a poor 5-year overall survival." (PMID 38201468, 2023). "The interaction of CD44 with hyaluronic acid in ovarian cancer also results in the activation of NANOG–STAT3." (PMID 38201468, 2023). "For example, EVs from highly invasive ovarian cancer cell lines that characteristically overexpress CD44 can reprogramme ovarian cancer cells with low aggressiveness that have engulfed EVs into cells with a more aggressive phenotype." (PMID 37735659, 2023). "As previously discussed, CD44 is an adhesion molecule found on ovarian cancer cells having high affinity for hyaluronic acid; the interaction between the two is thought to be a key modulator of HGSOC cell adhesion." (PMID 35574025, 2022). "The significant association of only peritumoral cancer-cell HA deposition with high CD44 mRNA expression levels suggests a pivotal role of the CD44–HA signaling axis for malignant progression in ovarian cancer." (PMID 36428513, 2022). "Magnetic-induced-heating PEG-MZF-NPs/DDP/CD44-shRNA nanoliposomes provide a new and feasible method for ovarian cancer treatment." (PMID 35402279, 2022). "CD44 expression in ovarian cancer cells is crucial in binding hyaluronan, and TNFα, which is secreted by adipocytes, has been reported to induce the expression of CD44 in ovarian cancer cells through activation of JNK." (PMID 35565396, 2022). "Upregulation of VCAN in CAFs enhanced ovarian cancer cell motility and invasion potential by activating the NF-κB signaling pathway and upregulated expression of CD44, MMP9 and the hyaluronan mediated motility receptor." (PMID 36203562, 2022). "Other than that, CD44 is highly expressed in ovarian cancers’ drug-resistant cells and advanced epithelial tissues and has been considered a marker for poor ovarian cancer prognosis." (PMID 35402279, 2022). "As an integral membrane protein with multifunctional adhesion ability, CD44 plays a vital role in cancer progression, including ovarian cancer." (PMID 35907907, 2022). "We next investigated the expression of ovarian cancer biomarkers and CD44 (n=6) in HGSOC using multiplex immunohistochemistry." (PMID 36789687, 2022). "Studies on ovarian cancer cells have shown that CD44 expression is increased in drug-resistant cancer cells and that CD44 appears to play an important role in paclitaxel resistance." (PMID 35715750, 2022). "Previously, we reported that different ovarian cancer cell types are derived from CD44+/MyD88+ EOC stem cells with lost stemness." (PMID 36123378, 2022).
ovarian carcinoma (continued). "These biological behaviours of CDC50A+ ovarian cancer cells were consistent with those of ovarian cancer cells with positive expression of several classic stem cell surface biomarkers, such as CD44, CD117, CD24 and CD133." (PMID 35982417, 2022). "It has been shown that inhibition of CD44 inhibits the development of colon tumors in mice and suppresses the proliferation and metastasis of liver and ovarian cancer cells." (PMID 36389678, 2022). "Osteopontin/CD44 cascade promotes ovarian cancer cell chemoresistance via PI3K/AKT signaling and drug efflux mechanisms." (PMID 35464064, 2022). "Here, we isolated tumorspheres or an ALDH+CD44+ cell subset from ascites or ascites-originating ovarian cancer cell lines (SKOV3 and OVCAR3) and compared the PFKFB3 expression between the CSC-enriched subpopulation and non-CSCs." (PMID 35155224, 2022). "Co-treatment of shear stress and HGF resulted in upregulation of ALDH3 and ovarian cancer stemness marker CD44, which was abrogated in the presence of miR-199a-3p overexpression." (PMID 35676254, 2022). "The migration and invasion of ovarian cancer cells with low metastatic potential are promoted by exosome-mediated transfer of CD44 from ovarian cancer cells with high metastatic potential." (PMID 36210808, 2022). "Exosomes derived from epithelial ovarian cancer cells have been found to promote ovarian cancer invasion by transferring CD44 to human peritoneal mesothelial cells." (PMID 34900338, 2022). "LncRNA WDFY3-AS2 promotes cisplatin-resistant and CD44+CD166+cells in ovarian cancer by regulating the hsa-miR-139-5p/SDC4 axis." (PMID 36437919, 2022). "Exosomes derived from ovarian cancer cells transported CD44 to human peritoneal mesothelial cells, thus increasing the invasive ability of ovarian cancer." (PMID 35024437, 2022). "Bclxl is upregulated in CD44+/MyD88+ chemoresistant ovarian cancer stem cells compared to CD44−/MyD88− sensitive ovarian cancer cells." (PMID 35565396, 2022). "In this study, ovarian cancer HO8910 cells were transfected with CD44-shRNA plasmids by using PEG-MZF-NPs as gene transferring vector." (PMID 35402279, 2022). "Up-regulated VCAN promotes motility and invasion of ovarian cancer cells by activating the NF-κB signaling pathway and up-regulating the expression of CD44, matrix metalloproteinase 9, and hyaluronan-mediated motility receptors." (PMID 35812745, 2022). "Several other Igf2bp1 target RNAs (SRF, cMyc, and CD44) are reduced in lung and ovarian carcinoma cells incubated with the compound." (PMID 34895045, 2022). "It has been proven that CD44 is highly expressed in ovarian cancer, and its aberrant expression plays a crucial role in ovarian cancer occurrence, development, invasion, and metastasis." (PMID 35402279, 2022). "The binding of CD44 to HA has been shown to promote ovarian cancer cell binding to peritoneal tissue and ovarian cancer cell migration." (PMID 36494669, 2022). "Other ovarian cancer stem cells (OCSCs), identified by surface markers CD44, Prominin 1 (PROM1, CD133), and Aldehyde Dehydrogenase 1 Family Member A1 (ALDH1A1), reportedly involved in EOC development, relapse, and chemoresistance." (PMID 35401749, 2022). "Following the interaction of CD44 with HA, ankyrin binds to multidrug resistance mutation 1 (MDR1) leading to doxorubicin efflux and paclitaxel and chemoresistance in both breast and ovarian cancer cells." (PMID 35464064, 2022). "In our preclinical models of ovarian cancer, tumors with high CD44 expression were more likely to respond to APG-2449/paclitaxel, and the combination also significantly reduced CSC populations expressing either ALDH1 or CD44." (PMID 35820889, 2022). "In vitro assessment of cellular uptake in CR SKOV-3 cells revealed a preferential uptake of HA@MOF@Cy 5.5 into CR SKOV-3 ovarian cancer cells overexpressing CD44 (a cell surface glycoprotein)." (PMID 36419626, 2022).